MIR609 (microRNA 609)
Synonyms: hsa-mir-609; MIRN609
Gene: MicroRNA gene on chromosome 10 (104,218,789 to 104,218,883, reverse strand). Ensembl gene ENSG00000208033.
Gene Ontology:
Biological process: miRNA-mediated post-transcriptional gene silencing
Cellular component: RISC complex
Homologues: Orthologues: chimpanzee ptr-mir-609 (100% identical), macaque mml-mir-609 (94% identical).